MBD3L2 (methyl-CpG binding domain protein 3 like 2)
Description:
May displace the NuRD complex from chromatin.
Tractability: No criterion of Open Targets' tractability assessment is met for any kind of drug.
Gene: Protein-coding gene on chromosome 19 (7,049,321 to 7,051,735, forward strand). Ensembl gene ENSG00000230522.
Subcellular location: Nucleus
Subcellular location (Human Protein Atlas): Nucleoli; Nucleoplasm; Cytosol
Pathways (Reactome):
Chromatin organization: NuRD complex assembly
Gene Ontology:
Molecular function: protein binding; methyl-CpG binding
Biological process: regulation of chromatin organization; regulation of transcription by RNA polymerase II; DNA methylation-dependent constitutive heterochromatin formation; negative regulation of transcription by RNA polymerase II
Cellular component: nucleus; nucleoplasm
Homologues: Orthologues: rat Mbd3l2 (42% identical), rat Mbd3l3 (39% identical), mouse Mbd3l2 (39% identical), zebrafish mbd3a (31% identical), tropical clawed frog mbd3 (31% identical), Drosophila melanogaster MBD-like (22% identical). Paralogues in human: MBD3L5 (99% identical), MBD3L2B (98% identical), MBD3L3 (98% identical), MBD3L4 (98% identical), MBD3L1 (36% identical), MBD2 (32% identical), MBD3 (32% identical), MBD1 (21% identical).
Diseases named in the same sentence as MBD3L2 in open-access papers:
MBD3L2 is named in the same sentence as 5 diseases in open-access papers, as found by Europe PMC text mining. Sharing a sentence is not in itself a finding about the gene and the disease. The quoted sentences say what the papers report.
pancreatic cancer (7 papers, 2015 to 2025). "The analysis of biomarkers in saliva offers an easy and noninvasive way to search for mutations in RNAs and miRNAs of genes such as MBD3L2, KRAS, ACRV1 and DPMI, among others, which could assist in differentiating pancreatic cancer patients from CP patients and healthy control." (PMID 38338919, 2024). "mRNA biomarkers (KRAS, MBD3L2, ACRV1, DPM1) can differentiate pancreatic cancer patients from healthy individuals." (PMID 39958008, 2025). "Biomarker proteins in pancreatic cancer include KRAS (Kirsten Rat Sarcoma Viral Oncogene), MBD3L2 (Methyl-CpG Binding Domain Protein 3 Like 2), DPMI mRNAs (Dolichol phosphate mannose synthase), and ACRV1 (Acrosomal Vesicle Protein 1)." (PMID 39091905, 2024). "Studies have identified KRAS, MBD3L2, ACRV1, and DPM1 as biomarkers in salivary mRNA to detect pancreatic cancer with high specificity." (PMID 38202898, 2023). "In pancreatic cancer, the salivary messenger RNA can be used to detect KRAS, Methyl-CpG Binding Domain Protein 3-Like 2 (MBD3L2), Acrosomal Vesicle Protein 1 (ACRV1) and Dolichyl-Phosphate Mannosyltransferase Subunit 1 (DPM1) with 90% sensitivity and 95% specificity." (PMID 32294884, 2020).
MBD3L2 also shares sentences with these, for which no sentence is quoted: cancer (2 papers); chronic pancreatitis (1); pancreatitis (1); tumour (1).